RABL6 (RAB, member RAS oncogene family like 6)
Description:
Small GTPase involved in the regulation of cell growth and survival. Promotes cellular proliferation. May reduce growth inhibitory activity of CDKN2A.
Synonyms: RBEL1; C9orf86; PARF; FLJ10101; FLJ13045; pp8875; bA216L13.9
Tractability: PROTAC: ubiquitination databases record sites on it; its protein half-life has been measured.
Gene: Protein-coding gene on chromosome 9 (136,807,927 to 136,841,187, forward strand). Ensembl gene ENSG00000196642.
Subcellular location: Cytoplasm (Isoform 1); Nucleus (Isoform 3)
Subcellular location (Human Protein Atlas): Centrosome; Cytosol; Basal body; Centriolar satellite
Gene Ontology:
Molecular function: GTP binding; protein binding; G protein activity
Cellular component: cytoplasm; cytosol; nucleus
Genetic constraint (gnomAD): Loss-of-function variants: 25 observed, 59.35 expected, observed/expected ratio (o/e) 0.42, 90% interval 0.31 to 0.59. The synonymous counts are far from expectation, so gnomAD's model fits this gene poorly and the ratio says little. Missense variants: 1,004 observed, 869.88 expected, observed/expected ratio (o/e) 1.15, 90% interval 1.1 to 1.22. Synonymous variants: 464 observed, 370.86 expected, observed/expected ratio (o/e) 1.25, 90% interval 1.16 to 1.35.
Homologues: Orthologues: chimpanzee RABL6 (99% identical), macaque RABL6 (95% identical), rat Rabl6 (80% identical), mouse Rabl6 (80% identical), dog RABL6 (78% identical), guinea pig RABL6 (78% identical), pig RABL6 (60% identical), zebrafish rabl6b (60% identical), tropical clawed frog rabl6 (54% identical), zebrafish rabl6a (42% identical), Caenorhabditis elegans F08G12.1 (32% identical).
Diseases named in the same sentence as RABL6 in open-access papers:
RABL6 is named in the same sentence as 16 diseases in open-access papers, as found by Europe PMC text mining. Sharing a sentence is not in itself a finding about the gene and the disease. The quoted sentences say what the papers report.
breast carcinoma (9 papers, 2013 to 2024). "RABL6 is markedly upregulated in breast cancer, gastric cancer, osteosarcoma, oesophageal squamous cell carcinoma and pancreatic neuroendocrine tumours and is significantly associated with tumour invasion, metastasis and prognosis." (PMID 38879667, 2024). "Specifically, RABL6 is highly expressed in breast cancer and promotes cell invasion while stimulating cell proliferation by facilitating entry into the G1 phase and inhibiting apoptosis." (PMID 38879667, 2024). "Recently, non-small cell lung cancer (NSCLC), breast cancer and pancreatic ductal adenocarcinoma have been showed to overexpress RABL6, and that was closely correlated with poor prognosis." (PMID 32600359, 2020). "RABL6 overexpression also indicates poor prognosis of breast cancer." (PMID 35681777, 2022). "RABL6 is a member of the RAS oncogene family, and its expression is elevated in breast cancer cell lines and tumor samples." (PMID 35681777, 2022). "Several studies have reported that RABL6 was highly expressed in many cancers, such as non-small cell lung cancer (NSCLC), breast cancer, and pancreatic ductal adenocarcinoma (PDAC), and is often related to the poor prognosis for the patients." (PMID 34745992, 2021). "In breast cancer cell lines SK-BR-3 and MCF-7, silencing of RABL6 by siRNA suppressed cell proliferation and invasion capabilities in vitro." (PMID 32600359, 2020). "In another previous study, we identified the same upstream effectors (ERBB2, RABL6, FOXM1 and MITF) to be the most effected by palbociclib treatment in the MDA-MB-231 breast cancer cells, reducing colony formation, cell migration and viability." (PMID 31835892, 2019). "Our findings from the current study are concordant with our previously published work on transcription factors such as ERBB2, RABL6, FOXM1 and MITF which are most effected by palbociclib treatment in MDA-MB-231 breast cancer cells, reducing colony formation, cell migration and viability." (PMID 34565361, 2021).
gastric cancer (3 papers, 2023 to 2024). A primary or metastatic malignant neoplasm involving the stomach. "RABL6 is upregulated in gastric cancer and is associated with immune regulation and immune cell infiltration." (PMID 38879667, 2024). "Contrastingly, some studies have shown that miR-361-3p can act as a tumor suppressor gene, such as in gastric cancer, where it targets TGFB1 or RABL6 to inhibit the progression and metastasis of gastric cancer." (PMID 38282047, 2024).
osteosarcoma (3 papers, 2018 to 2024). A usually aggressive malignant bone-forming mesenchymal neoplasm, predominantly affecting adolescents and young adults. "In osteosarcoma, RABL6 acts as an oncogenic driver by regulating the cell cycle by inhibiting Rb protein activity and participating in the p27–Rb1 axis." (PMID 38879667, 2024). "RABL6 regulated retinoblastoma 1 (Rb1) activity in osteosarcoma cells, which was the major player in cell cycle control." (PMID 32600359, 2020). "RABL6 has been reported to promote proliferation of osteosarcoma and pancreatic neuroendocrine tumor through inhibition of retinoblastoma 1 (pRb)." (PMID 30042885, 2018). "Similarly, knocking down of RABL6 in osteosarcoma cells also impaired cell colony formation and proliferation." (PMID 32600359, 2020).
breast tumors (2 papers, 2013 to 2020). "Several studies found elevated RABL6 expression in various human cancers, including pancreatic ductal adenocarcinomas, pancreatic neuroendocrine tumors and breast tumors." (PMID 32600359, 2020).
urothelial bladder cancer (2 papers, 2023 to 2024). "Additionally, ALYREF contributes to the malignancy of urothelial carcinoma of the bladder (UCB) by maintaining the stability of RABL6 and TK1 mRNA30." (PMID 38491127, 2024).
bladder cancer (1 paper, 2025). "Through its K171 domain, ALYREF recognizes RABL6 and TK1 mRNA m5C modification, promoting their mRNA splicing and stability to increase bladder cancer malignancy." (PMID 40809690, 2025). "Specifically, m5C-mediated ALYREF recognizes RABL6 and TK1 mRNA m5C modification through its K171 domain, enhancing mRNA splicing and stability to increase bladder cancer malignancy." (PMID 40809690, 2025).
leukemia (1 paper, 2020). A malignant (clonal) hematologic disorder, involving hematopoietic stem cells and characterized by the presence of primitive or atypical myeloid or lymphoid cells in the bone marrow and the blood. "Specifically, the differentially expressed gene RAS oncogene family like 6 (RABL6, also known as RBEL1 and C9orf86), CD93, and Zinc Finger Protein 709 (ZNF709) have been implicated in cancers and leukemia." (PMID 32134197, 2020).
liver cancer (1 paper, 2021). An epithelial or non-epithelial malignant neoplasm that arises from the liver. "In conclusion, our study found that AR could suppress liver cancer cells invasion and proliferation capacities via miR-122-5p/RABL6 signaling, and miR-122-5p could suppress the expression of RABL6 to influence liver cancer cells progression by directly targeting the 3’UTR of RABL6-mRNA." (PMID 34745992, 2021). "Here, our study showed that AR could suppress liver cancer cells invasion and proliferation capacities via miR-122-5p/RABL6 signaling, and miR-122-5p could suppress the expression of RABL6 to influence liver cancer cells progression by directly targeting the 3’UTR of RABL6-mRNA." (PMID 34745992, 2021).
cancer (10 papers, 2013 to 2025). A tumor composed of atypical neoplastic, often pleomorphic cells that invade other tissues. "In future studies evaluating the relevance of RABL6 to cancer, it will be essential to determine the mutational status of the RABL6 gene and relative protein expression levels of the different RABL6 isoforms in tumors versus benign tissue." (PMID 24282525, 2013). "And RABL6 overexpression was associated with poor survival in those cancers." (PMID 32600359, 2020). "The average fold change of RABL6 mRNA was obviously higher in all tested cancer cell lines compared with NE-1 and Het-1A, except KYSE150." (PMID 32600359, 2020). "Compared with Het-1A, western blot analysis showed that RABL6 expression was higher in cancer cell lines." (PMID 32600359, 2020). "Among them, up-stream tyrosine kinase receptor ErbB-2, Rab-like protein 6 (RABL6), microphthalmia-associated transcription factor (MITF), which are involved in progression and development of several types of cancer were predicted to be suppressed." (PMID 31671612, 2019). "Microarray database analyses support that notion since altered levels of RABL6 mRNA, both increased and decreased, exist in a significant number of human cancers." (PMID 24282525, 2013). "While more needs to be learned about the RABL6 proteins, especially their significance and mechanisms of action in cancer and ARF signaling, the findings presented herein represent an important advance in understanding RABL6A." (PMID 24282525, 2013). "RAB, member RAS oncogene family like 6 (RABL6), a member of the RAS subfamily, has been reported as an important molecule in several cancers." (PMID 32600359, 2020). "Additionally, 8 upstream regulatory proteins were predicted to be activated, including Rab-like protein 6 (RABL6), heat shock factor 1 (HSF1), epidermal growth factor (EGF), and ERBB2, all of which are involved in the progression of various cancers." (PMID 40301999, 2025). "RABL6 and TK1 are well-known oncogenes and promote tumor proliferation in many types of cancers." (PMID 36806253, 2023). "Our study was the first to check RABL6’s role in HCC, and found that RABL6 also could work as an oncogene to promote HCC progression, which was consistent with its role in other cancers." (PMID 34745992, 2021). "Owing to RABL6 high-expression predicted poorer prognosis in ESCC patients, we raised a hypothesis that RABL6 might play oncogenic roles in ESCC, and RABL6 expression might promote cancer cell growth." (PMID 32600359, 2020). "Based on the WGS data for 13 patients and TES data from an expanded cohort of 69 T-ALL cases that were integrated with LOH data, we identified 151 mutated genes, of which two genes had not been observed before in human cancer (RABL6 and IGHV3-64)." (PMID 27997540, 2016). "Two genes, RABL6 (a GTP-binding member of the Ras superfamily of small GTPases) and IGHV3-64, have not previously been reported in mutated form in human cancer." (PMID 27997540, 2016).
tumor (10 papers, 2013 to 2024). "The decreased rate of tumor progression in Rabl6 deficient mice was associated with a moderate but reproducible extension in survival in both NC and NP animals." (PMID 35571990, 2022). "Compared with patients without a smoking history, those with a smoking history (including both former and active smokers) had significantly higher RABL6 expression in tumour tissues and more pronounced co-localisation of RABL6 with CHRNA5." (PMID 38879667, 2024). "The result indicated that the m5C level of RABL6 was higher in tumor tissue than that in normal tissues." (PMID 36806253, 2023). "After knockdown of ALYREF, the inhibited colony formation and subcutaneous tumor formation were partially rescued by expressing RABL6 with WT m5C-site." (PMID 36806253, 2023). "Suppressing RABL6 expression inhibits tumor cell proliferation and invasion, while low RABL6 increases cell-cycle arrest and apoptosis." (PMID 35681777, 2022). "In vitro studies showed that knockdown of RABL6 inhibited tumor cell growth, proliferation, invasion and migration." (PMID 32600359, 2020). "Migration assays showed that RABL6 could not rescued reduced tumor cell migration capacity caused by ALYREF." (PMID 36806253, 2023). "Whether RABL6 promoted tumor cell migration via inducing EMT remains unclear." (PMID 32600359, 2020). "No statistical association was found between expression of RABL6 and other clinicopathological characteristics such as gender, tumor location, peri-neural invasion, histological differentiation, pathological stage, and lymph node metastatic status in our study." (PMID 32600359, 2020). "Mice lacking Rabl6 displayed significantly slower kinetics of tumor growth and time for tumors to triple in both NC and NP genetic settings." (PMID 35571990, 2022). "Mice lacking Rabl6 displayed slower tumor progression and extended survival relative to wildtype animals in both genetic contexts." (PMID 35571990, 2022). "RABL6 belongs to the RAB proteins family, considered as the key regulators of intracellular trafficking that can promote proliferation, migration and invasion of tumor cells through co-ordinating different signaling pathways cross-talk." (PMID 29202775, 2017). "First, the global Rabl6 knockout mouse employed herein causes loss of RABL6A expression in nontumor host cells, such as tumor-associated fibroblasts and blood vessels, that could influence tumor progression independent of direct effects on the tumor cells." (PMID 35571990, 2022).
RABL6 also shares sentences with these, for which no sentence is quoted: pancreatic ductal adenocarcinoma (2 papers); pancreatic neuroendocrine tumor (2); breast (1); esophageal squamous cell carcinoma (1); hepatocellular carcinoma (1); non-small cell lung carcinoma (1).